DNMT3B (DNA methyltransferase 3 beta)
Diseases named in the same sentence as DNMT3B in open-access papers (continued):
Sharing a sentence is not in itself a finding about the gene and the disease.
tumor (continued). "In addition, polymorphisms in the DNMT3B gene may influence its enzymatic activity, and the SNPs in the DNMT3B promoter that play a role in de novo methylation have also been reported to be associated with several tumor susceptibilities." (PMID 24069326, 2013). "In details, expression of DNMT3B in tumor tissues was directly related with lymph node ratio, expressed as total involved lymph nodes over total number of resected lymph nodes (r = 0.37, P = 0.046)." (PMID 22919364, 2012). "Inhibition of DNMT1 is crucial for disrupting the aberrant methylation at tumor-relevant genes and inhibition of DNMT3B is probably needed to interfere with de novo methylation." (PMID 22563479, 2012). "Expression of DNMT3b protein also marginally associated with prolonged DFS in postmenopausal patients (P = 0.098) and patients whose tumor occurred in both sides (P = 0.097)." (PMID 22768205, 2012). "DNMT3B overexpression in tumor tissue was positively correlated with both lymph nodes spreading (P = 0.046) and resection margin status (P = 0.04), and a borderline association with perineural invasion (P = 0.06) was found." (PMID 22919364, 2012). "Earlier publications reported the downregulation of DNMT3B by miR-29b or miR-383 particularly in tumor cells." (PMID 21559294, 2011). "This evidence has been further confirmed showing that the selective silencing of DNMT1 and DNMT3b greatly reduces the chemoresistance of tumor cells overexpressing DNMTs isoenzymes." (PMID 21108789, 2010). "DNMT1, DNMT3A and DNMT3B were substantially over-expressed in human hepatocarcinogenesis accompanied by a marked increase of tumor suppressor genes methylation." (PMID 21629434, 2010). "Genetic disruption of both DNMT1 and DNMT3B resulted in greater than 95% reduction in genomic cytosine-5 DNA methylation and re-activation of silenced tumor suppressor genes." (PMID 21629434, 2010). "Studies on the depletion of DNMT1 and DNMT3B in tumour cells have implied that they play an important role in tumour development." (PMID 20128888, 2010). "Compared with inhibition of DNMT1, DNMT3B siRNA induced more tumor-related genes identical to that of demehylation drug 5-aza-2’-deoxycytidine." (PMID 27994704, 2008). "DNMT3b is frequently overexpressed in tumor cells and its expression has been correlated with decreasing differentiation." (PMID 17938735, 2007). "DNMT3B also has similar effects to a tumor suppressor in hematopoietic cells." (PMID 39819598, 2025). "Following the hypothesis that the tumours with ectopic activation of DNMT3B target the silencing of a number of onco-suppressor genes, primarily GATA3, we performed a GSEA in two different contexts, separately." (PMID 40585280, 2025). "Additionally, studies indicate that DNMT3B is a tumor suppressor in Myc-induced lymphomas and MLL-AF9-driven AML." (PMID 39996888, 2025). "Similarly, DNMT3B knockdown decreases cell proliferation, migration, and invasion in HeLa3rd (a HeLa subline) and CaSki, as well as in vivo tumor growth and metastasis." (PMID 41226543, 2025). "Furthermore, it has been reported that estrogen reduces FAM111B expression by DNMT3B methylation and facilitates tumor growth in PTC." (PMID 38890707, 2024). "Considering that the PI3K/Akt pathway participates in chemoresistance and mediates DNMT3B expression, we could reasonably postulate that DNMT3B inhibition plays a tumor suppressor role in GBM in a PI3K/Akt pathway-dependent manner." (PMID 38368287, 2024). "Moreover, CHIR-99021 markedly improved the efficacy of sorafenib in HCC- multicellular tumor spheroids in vitro and through induction of apoptosis by decreasing DNMT3B expression in vivo." (PMID 38168140, 2024). "DNMT3B influences tumor development through its enzymatic activity." (PMID 39185313, 2024). "In addition, the interplay between non-coding RNA and DNMT3b can significantly influence tumor cell fate." (PMID 38879516, 2024).
tumor (continued). "Additionally, fresh tissue samples were collected for protein extraction, and the western blot analysis results demonstrated high expression of DNMT3B in the tumor tissues." (PMID 39108206, 2024). "Similarly, DNMT3B overexpression has been correlated with increased methylation levels and tumor progression." (PMID 39370455, 2024). "Inhibiting DNMT3B can reduce the degree of methylation of tumor suppressor genes by facilitating demethylation, thereby significantly decreasing the proliferation and invasion ability of tumor cells." (PMID 38368287, 2024). "Western blot analysis results demonstrate high expression of DNMT3B in tumor tissues." (PMID 39108206, 2024). "Thus, YTHDF1 promotes the progression of GC by upregulating DNMT3B, and inhibiting DNMT3B contributes to reduce the tumor promotion ability of YTHDF1." (PMID 39185313, 2024). "Additionally, we discovered that the levels of three DNA methyltransferases (DNMT1, DNMT3A, and DNMT3B) were significantly higher in the CBX2high tumor than the CBX2low tumor and the CEP55high tumor than the CEP55low tumor." (PMID 37980163, 2023). "Interestingly, CpG73 methylation levels were also inversely correlated with DNMT3B expression, suggesting that CpG73 hypermethylation in tumor cells is determined independently of DNMT3B." (PMID 37367043, 2023). "This independently supported the hot anti-tumour TIME induced by DNMT3B amplification." (PMID 37277866, 2023). "Furthermore, we determined the expression of the members of the DNA methyltransferase family (DNMT1, DNMT3a, and DNMT3b) in tumor tissue by immunohistochemistry." (PMID 37175434, 2023). "Interestingly, DNMT3A, a paralogue of DNMT3B, predominantly plays a tumor-suppressive role in cancers." (PMID 37072414, 2023). "Among them, DNMT3b, DNMT1, ALYREF, TET2, NSUN2 and NSUN5 mutations imply that m5C may act abnormally in the tumour." (PMID 37408139, 2023). "Furthermore, it was observed by the researchers that the restraining of DNMT3B expression exhibited comparable effects in suppressing tumor growth, as seen with the induction of miR-26a overexpression." (PMID 37705098, 2023). "Additionally, they have demonstrated that DNMT3B plays a critical role in tumor invasion, thereby highlighting its potential as a viable therapeutic target for addressing metastatic diseases." (PMID 37705098, 2023). "Similarly, the mRNA levels of DNMT3A and DNMT3B were increased in tumor tissues compared with control groups." (PMID 35620052, 2022). "Thereafter, we determined the relevance of miR-149 to DNMT3B expression in the tumor tissues." (PMID 35129056, 2022). "miR-29c-3p inhibits tumor progression by regulating the methylation of DNMT3B and LATS1 in LIHC." (PMID 35574298, 2022). "An elegant in vivo study highlighted that resveratrol may differentially influence the expression of DNA methyltransferase 3b (DNMT3b) and miRNAs in tumor tissue vs. normal tissue in a dose-dependent manner." (PMID 35912113, 2022). "First, we used RT-qPCR to indicate that the level of DNMT3b was higher in HCC tumor tissues." (PMID 35795047, 2022). "Overall, these data suggest that the expression of DNMT3B enhances DNA methylation during ccRCC progression, which may be important in tumor formation and related to poor patient outcomes." (PMID 34133843, 2022). "Here, analysis of the correlation between CARM1 and four methyltransferases (DNMT1, DNMT2, DNMT3a, DNMT3b) expression was conducted for each tumor to explore whether CARM1 expression is related to epigenetics." (PMID 35033016, 2022). "Here, we report the tumor progressive role of DNMT3B in ccRCC." (PMID 34133843, 2022). "Since we recently demonstrated the up-regulation of both DNMT3A and DNMT3B transcript levels in RMS tumour samples compared to normal skeletal muscle and the antitumoral effects of DNMT3B knocking down on ERMS cell lines, here, we analysed DNMT3A/3B involvement in radioresistance mechanisms." (PMID 34831178, 2021).
tumor (continued). "Another interesting finding is that Dnmt3bCI/CI mice had decreased tumor incidence relative to Dnmt3b+/CI (from 35% to 31%) and changed disease spectrum, which is surprising as full CA inactivation would be predicted to promote, rather than suppress, tumorigenesis." (PMID 33450231, 2021). "Indeed, experimental evidence suggests that DNMT1 and DNMT3B are responsible for p16 promoter hyper-methylation, this leading to its inactivation in several tumours." (PMID 34831178, 2021). "DNMT3B was significantly correlated with the degree of tumor cell differentiation (p = 0.030)." (PMID 34616614, 2021). "We found NDRG1 expression was significantly inverse correlated with invasion depth (p = 0.023), whereas DNMT1 was statistically significantly positive correlated with invasion depth (p = 0.049), DNMT3B was significantly positive correlated with the degree of tumor cell differentiation (p = 0.030)." (PMID 34616614, 2021). "The activation of STAT3 signaling and the inhibited expression of SOCS3 may be responsible for aggressive tumor growth in DNMT3b-positive ESCC cells." (PMID 34691358, 2021). "We demonstrate that combined treatment with GSK126 and 5-Aza-2’-deoxycytidine to inhibit methyltransferase activity of EZH2 and DNMT3B synergistically block EC cell proliferation and EC tumor progression in both cell line-derived xenograft (CDX) and patient-derived xenograft (PDX) mouse models." (PMID 34175897, 2021). "Moreover, Dnmt3b is a tumor suppressor in oncogene-driven lymphoid and myeloid malignancies in mice." (PMID 33450231, 2021). "miRNAs may also play a significant role in the DNA methylation pattern, as, for example, miR-29 inhibits DNMT3a and DNMT3b enzymes in several tumor types." (PMID 33878138, 2021). "DNMT3B was significantly positive correlated with the degree of tumor cell differentiation." (PMID 34616614, 2021). "Several studies have indicated that miR-34a suppressed the migration and invasion of tumor cells by down-regulating HNF4γ and Notch1, consistent with our hypothesis that DNMT3B may play its role by miR-34a-HNF4γ and/or Notch1 axis." (PMID 33221743, 2020). "This work suggests that DNMT3B has an anti-tumor effect in T cells." (PMID 32751889, 2020). "Moreover, in previous studies, the protein expression of both DNMT3a and DNMT3b was found to be increased in tumor cell lines." (PMID 32908633, 2020). "Here, a significantly decreased expression of Dnmt1 and Dnmt3b was recorded early after tumor cell implantation, which indicates a reduced DNA-methylating activity and could explain the increased expression of EdnrB and/or Ece1 mRNA." (PMID 32194414, 2020). "In the present study, however, we observed a positive association between DNMT3B expression and survival probability among CRC patients after surgery, inconsistent to what we expected, therefore we assume that DNMT3B is likely to have a tumor suppressing effect in colorectal carcinogenesis." (PMID 31024853, 2019). "We next measured the levels of DNMT1, DNMT3A and DNMT3B in these tumor tissues." (PMID 30948928, 2019). "The number of altered methylation probes was varied from 26 to 234 across tumor types, and these changes may be contributed by high expression of DNMT3B (Supplementary )." (PMID 31828117, 2019). "Demethylation drugs that inhibit DNMT3B expression reduce the degree of methylation of tumor suppressor genes, thus restoring the expression of these genes and thereby significantly decreasing the proliferation and invasion ability of tumor cells." (PMID 30718452, 2019). "We have noted upregulation of DNMT3B in OSCC-GB tumor samples driven by promoter hypomethylation." (PMID 31796082, 2019). "In addition, we detected proliferation-related proteins (Ki67, Bcl-2 and cyclin D1), CSCs core genes and DNMT3B levels in tumor grafts to investigate the mechanism by which antisense inhibition of piRNA-823 reduced the tumor volume in vivo." (PMID 30979371, 2019).
tumor (continued). "Therefore, DNMT3B appears to act primarily as an oncogene, and in some tumor types, its overexpression is an unfavorable prognostic marker." (PMID 30406101, 2018). "Abnormal expression of DNMT3B is related to the hypermethylation of the tumor suppressor genes." (PMID 29796115, 2018). "Hence, we conclude that DNMT3B contributes to tumor maintenance of MYC-driven T-ALL through its effects on DNA methylation, and that loss of DNMT3B causes the reactivation of gene transcription through reversing CpG island methylation." (PMID 29100357, 2017). "This suggests a differential role of DNMT3B during tumor initiation versus maintenance." (PMID 29100357, 2017). "While the only commercially available DNMT3B inhibitor (NA) exhibited a broad cytotoxic response, we conclude that specific shRNA-mediated knock-down of DNMT3B decreased tumor cell proliferation by upregulating tumor suppressor genes and triggering a cell cycle arrest rather than cell death." (PMID 29100357, 2017). "Thus, HMA appears to have to inhibit DNMT3a and DNMT3b as well as DNMT1 to exert anti-tumor activities." (PMID 28052028, 2017). "DNMT3B target therapies may represent a novel clinical approach, effective not only in impairing tumour growth but also in reactivating myogenic program, especially in ERMS subtypes." (PMID 27764816, 2016). "Indeed, knock-down of DNMT3B gene by RNA interference impaired the in vitro tumour-promoting potential of ERMS cells by significantly reducing cell proliferation, migration and colony-forming ability." (PMID 27764816, 2016). "The possible explanation is the increased promoter activity of DNMT3B by this C to T transition might up-regulate genes that involve in regulation of methylation of some tumor suppressor genes." (PMID 27876061, 2016). "However, Dnmt3b has been shown to behave as a tumor suppressor gene in mouse models of Myc-induced T- and B-cell lymphomas." (PMID 27563627, 2016). "DNMT3b may participate in gene methylation in multiple tumors, which can be used as early biomarkers in the early diagnosis of a tumor." (PMID 25886188, 2015). "Overall, these findings suggest that DNMT3B could be a useful target for the induction of tumor-selective radiosensitization." (PMID 26667181, 2015). "Enhanced radiosensitivity by DNMT3B RNAi was also observed in a tumor xenograft model." (PMID 26667181, 2015). "Furthermore, an inverse correlation of RNA levels between miR-129, 204, 489, and DNMT3b was seen in normal tissue; in tumor tissue, this was only observed for miR-489." (PMID 26075205, 2015). "To investigate the factors involved in TSG hypermethylation in NSCLC, we attempted to determine whether DNMT1 and DNMT3B RNA expression levels correlated with the hypermethylation of the promoters of the studied tumor suppressor genes." (PMID 26112163, 2015). "DNMT3b is perceived as the prevalent methyltransferase in breast carcinogenesis; hence, the inverse correlation between DNMT3b and miR-129 and 204 needs further examination with respect to its role in tumor development." (PMID 26075205, 2015). "We found higher DNMT1 mRNA levels compared to de novo DNMT in both tissues and in all experimental groups, according to the literature, and a coordinated expression of DNMT1, DNMT3a and DNMT3b in mammary gland and tumor, as it has been described in several tissues." (PMID 26401660, 2015). "In addition, the HCV core protein appears able to up-regulate the levels of DNMT1 and DNMT3b and to induce promoter hypermethylation of tumor suppressor genes like E-cadherin and p16, resulting in down-regulation of their expression." (PMID 26576645, 2015). "Notably, DNMT1, DNMT3A, and DNMT3B are overexpressed in a coordinate manner in most tumor tissues and at a significantly higher level in cancer than in non-tumorous tissues." (PMID 25949795, 2014).
tumor (continued). "DNMT3A and DNMT3B are highly expressed in early embryonic cells, the stage in which most programed de novo methylation events occur, are downregulated after differentiation and in adult somatic tissues, and are overexpressed in tumor cells." (PMID 24822169, 2014). "Accordingly, we suggested that DNMT3b overexpression plays a role in tumor promotion, and the induction of angiogenesis and EMT might be the underling mechanisms." (PMID 24625449, 2014). "The tumor aggressiveness noted in IL-6 positive OSCC may be in part via the overexpression of DNMT3b." (PMID 24625449, 2014). "In addition, DNMT3B expression was higher in patients with resection margins free of tumor cells (R0: median = 0.65, Q1–Q3 = 0.26–1.16), than in those with evidence of tumor infiltration on resected margins (R1: median = 0.20, Q1–Q3 = 0.12–0.42), P = 0.04." (PMID 22919364, 2012). "A nearly identical frequency of concordant and discordantfindings was obtained by analyzing the TCGA database (p<0.0001).Expression of DNMT1 and DNMT3b was strongly upregulated in tumor tissue, butnot correlated with MGMT promoter methylation and MGMT mRNAexpression." (PMID 21365007, 2011). "As DNMT3B is a de novo methyltransferase, we hypothesized that its contribution to the increased malignancy of the tumours might be due to its ability to silence some critical tumour suppressor genes following an ectopic DNA-methylation-dependent silencing of these genes." (PMID 40585280, 2025). "In summary, DNMT3B plays a multifaceted and complex role in the occurrence and development of tumors, and interventions targeting DNMT3B may potentially constitute a novel direction for tumor treatment." (PMID 40675967, 2025). "Interestingly, DNMT3B may act as a tumor suppressor in certain subtypes of AML, such as MLL-AF9 AML and inv (p13;q22) AML, highlighting a complex role in leukemia development." (PMID 39996888, 2025). "Considering our comprehensive analysis of DNMT expressions across the progression of OEC, we hypothesize that DNMT1 and DNTM3A seem to play a role in tumor initiation, DNMT3B in tumor progression and DNMT3L in tumor relapse, whereas DNMT2 may have an opposite role, acting as a tumor-suppressor gene." (PMID 37894317, 2023). "However, miR-148a expression was inversely correlated with the expression of DNMT1 (ρ = − 0.31, P = 0.04), whereas miR-148b expression showed negative correlation with the expression of DNMT3A (ρ = − 0.38, P = 0.02) and DNMT3B (ρ = − 0.33, P = 0.03) in tumor tissues from 42 NSCLC patients." (PMID 36959680, 2023). "The results showed that the expression of TYMS was negatively correlated with tumor mutational burden and microsatellite instability, and positively correlated with the expression of four methyltransferases (DNMT1: red, DNMT2: blue, Dnmt3A: green and DNMT3B: purple)." (PMID 35003215, 2021). "In addition, DNMT3B was confirmed to be directly regulated by miR-766-3p several years ago, and DNA methylation of some tumor suppressors such as DKK2 could be decreased by transfecting miR-766-3p-expressing viruses." (PMID 34093648, 2021). "Thus, whether DNMT3b acts as a tumor suppressor or promoter may depend on the tumor stage and specific tumor type." (PMID 31861404, 2019). "However, loss of Dnmt3a-but not Dnmt3b-increases the number of carcinogen-induced squamous tumors, without affecting tumor progression." (PMID 28425913, 2017). "Therefore, understanding the DNMT3B-mediated molecular mechanisms affecting these pathways may yield further insights into pathophysiological processes in RMS tumours." (PMID 27764816, 2016). "One of the potential mechanisms that underline the DNMT3B-mediated arrest involves the ability of DNMT3B siRNA to reduce the expression of different cyclins (Cyclin B1, Cyclin D1 and Cyclin E2) and to block the pRB/E2F1 pathway by inducing de-phosphorylation of RB tumour suppressor." (PMID 27764816, 2016).